CRP (C-reactive protein)
Diseases named in the same sentence as CRP in open-access papers (continued):
Sharing a sentence is not in itself a finding about the gene and the disease.
cancer (continued). "Upon surgical resection, the cancer cells undergo trauma, and such tumor cells can enhance the generation of cytokines and other factors, including IL-6, C-reactive protein (CRP), TNF-α, IL-1β to affect the immune system." (PMID 38566199, 2024). "Generally, high CRP and LDH levels and poor dietary intake are associated with organ damage and dehydration, which can be causes of AKI in advanced cancers." (PMID 38502665, 2024). "CRP contributes to cancer development by fostering an inflammatory environment, promoting tumour growth and survival, and modulating immune responses." (PMID 39498386, 2024). "Complete blood count (FBC), C-reactive protein (CRP), and albumin can reflect the systemic inflammatory status of cancer patients and thus predict prognosis to some extent." (PMID 38279138, 2024). "Serum markers of systemic inflammation, such as serum C-reactive protein and procalcitonin, have been identified as adverse prognostic factors in various cancers." (PMID 38919478, 2024). "CRP has been shown to be elevated in many cancers (e.g. NSCLC) and is correlated with poor outcomes." (PMID 38555313, 2024). "By scrutinizing the statistical relevance of CRP values in correlation with prognosis, grading, and size, we cautiously discern its involvement in fostering a cancer-friendly microenvironment, indicated by local recurrence and distant metastasis." (PMID 39001318, 2024). "The specificity of the anti‐CRP antibody was examined using a CRP‐gene‐transfected cancer cell line." (PMID 39564003, 2024). "Recently, studies have indicated a correlation between elevated CRP levels and poor prognostic outcomes in cancer patients." (PMID 39335753, 2024). "In patients with malignant tumors, CRP levels are modulated by cytokines, particularly interleukin-6, which is produced by tumor or surrounding cells." (PMID 39513125, 2024). "Our mediation analysis with clinical biomarkers for CVD and cancer revealed that CRP and SHBG partially medicated the effects of the omega-6/omega-3 ratio on all-cause mortality." (PMID 38578269, 2024). "We conducted subgroup analyses based on gender, age, BMI, eGFR, CRP, and medical history of cardiovascular disease and cancer." (PMID 38499679, 2024). "A notable correlation was identified between the level of CRP and the degree of differentiation of malignant tumors." (PMID 39335753, 2024). "Several studies have investigated the link between elevated CRP and poor survival in different cancer types." (PMID 38790938, 2024). "In cancer patients receiving n-3 LCPUFAs from fish oil supplements, inflammatory cytokines, including interleukin- 6 (IL-6), C-reactive protein (CRP) and tumor necrosis factor-alpha (TNFα), were found to be lower than those in control groups." (PMID 38308227, 2024). "A total of 143 participants were included in the study, of which 13 participants were excluded post-hoc: four patients developed nAMD, three were diagnosed with cancer, three died, one had CRP levels above 16, and two participants were lost to follow-up." (PMID 38165703, 2024). "Further validation using larger sample sizes (and across multiple cancer types) will be necessary to determine if sex-related differences in serum CRP levels (and perhaps even other cytokines) will be useful predictive biomarkers for immunotherapy." (PMID 39590174, 2024). "The combination of even modest reductions in albumin, reflective of chronic inflammation, combined with even modest elevations of markers of acute inflammation such as CRP and neutrophils, appear to be important predictors of survival in patients with cancer." (PMID 38404120, 2024). "C-reactive protein (CRP) was also higher in cancer patients at 6.45 mg/L, indicating a heightened inflammatory state." (PMID 39712803, 2024). "Higher-than-normal levels of C-reactive protein have been associated with poorer PFS and OS in patients with PD-1 inhibitor-treated cancers." (PMID 39741972, 2024).
cancer (continued). "Twenty‐two studies measured CRP as an endpoint, an acute‐phase protein with well‐documented prognostic value in cancer." (PMID 38783477, 2024). "C‐reactive protein (CRP) is a well‐known acute‐phase protein that increases remarkably under various inflammatory conditions and is elevated in patients with malignant tumors." (PMID 39564003, 2024). "CAR, was a combination of CRP and albumin, reflects the inflammatory state and nutritional state of cancer patients." (PMID 39098146, 2024). "Serial CRP evaluation among cancer patients hospitalized with acute bacterial infection can help pinpoint individuals with a good therapeutic response and potentially identify candidates for shorter, more individualized antibiotic therapy." (PMID 39272020, 2024). "TheCAR was first evaluated in patients with cancer, surgical patients and criticalillnesses and was found to have better predictive value than CRP or ALB alone foradverse outcomes." (PMID 39742221, 2024). "There is a potential role for the use of biomarkers in the diagnosis of cancer cachexia—human CC patients have been demonstrated to have elevated C-reactive protein (CRP), fibrinogen, IL1, IL6 and TNF-a." (PMID 38674936, 2024). "At baseline, patients with cancer had lower prealbumin and albumin levels (p< 0.001), higher CRP levels (p < 0.001), and lower UAMA percentiles (p = 0.0245) compared with controls." (PMID 39619813, 2024). "In subgroup analyses based on gender, age, BMI, eGFR, CRP, and medical history of cardiovascular disease and cancer, we observed that the ideal circadian exercise trajectory pattern consistently showcased a protective trend against T2DM risk." (PMID 38499679, 2024). "The levels of CRP, an acute-phase protein synthesized by the liver, increase rapidly in response to inflammation in patients with cancer." (PMID 38913646, 2024). "In this context, an elevated C-reactive protein (CRP) level and a high erythrocyte sedimentation rate (ESR) appears to be associated with a final diagnosis of cancer." (PMID 38622530, 2024). "The Glasgow Prognostic Score and modified Glasgow Prognostic Score using a combination of serum albumin and C-reactive protein have been reported in relation to postoperative prognosis in many cancers." (PMID 39594844, 2024). "Numerous cancers display higher CRP, reflecting both systemic inflammatory response and tumor progression, both significantly linked to patient prognosis and survival." (PMID 39070256, 2024). "In our analysis, we compared CRP, as a general marker of systemic inflammation, and IL-6, as a specific factor in emergence of cancer cachexia, as two biomarkers that would be easily accessible in routine clinical practice." (PMID 38539528, 2024). "Regarding cancer mortality prediction, the AUC values (95% CIs) were: CysC, 0.631 (0.590-0.672); eGFR, 0.614 (0.574-0.654); uric acid, 0.555 (0.513-0.597); CRP, 0.544 (0.502-0.586); creatinine, 0.542 (0.499-0.585); and urea nitrogen: 0.548 (0.503-0.593)." (PMID 38597157, 2024). "Performance status (PS), albumin levels, C-reactive protein (CRP), and body mass index (BMI) correlate with survival outcomes across cancer types." (PMID 39330032, 2024). "Several recent clinical studies have focussed on CRP level as a prognostic factor in ICI therapy for cancer." (PMID 39564003, 2024). "The CRP level reflects the inflammatory cytokines produced by cancer cells and the host immune response to cancer cells." (PMID 38730358, 2024). "Advanced age (p = 0.026) and a history of cancer (p = 0.016) were significantly correlated with heightened CRP levels (>0.30 mg/dL)." (PMID 39594253, 2024). "Increased CRP levels were reported as a sign of immune system activation in cancer, with important implications for the clinical management of this condition." (PMID 39596015, 2024). "The results showed that the possibility of cancer increased when CRP (C-reactive protein) > 3 mg/dl." (PMID 38627776, 2024).
cancer (continued). "The clinical implication of serum CRP levels in people affected by cancer cachexia needs to be further investigated, considering the impacts of systemic inflammation on the CNS and HPA axis, to improve their disrupted lives." (PMID 39765960, 2024). "While the clinical relevance of modestly increased CRP detectable by high-sensitivity CRP measurements (e.g. CRP between 3 and 10 mg/l) remains elusive for cancer patients, levels <3 mg/l are generally known to be reflective of good health and disease control." (PMID 38613909, 2024). "Elevated CRP levels have been observed in various types of cancers, often correlating with tumor progression and poorer prognosis." (PMID 38474160, 2024). "Elevated CRP levels occur in infections, inflammatory conditions, autoimmune and inflammatory diseases, injuries, or cancers." (PMID 38790615, 2024). "Patients with a high CRP level in the U-CAN validation cohort were found to have a significantly reduced 5-year cancer-specific patient survival compared to those with a low CRP level." (PMID 39613865, 2024). "In all, 356,554 participants were kept in the main analysis after excluding participants under the age of 18, those with prevalent cancer, those with less than one year of follow-up, and those with missing data in CRP, ALB, GLO, PLA, and WBC." (PMID 39314636, 2024). "Several systemic inflammatory biomarkers have been examined to predict prognosis in different types of cancer, including C-reactive protein (CRP), neutrophil-to-lymphocyte ratio (NLR), platelet-to-lymphocyte ratio (PLR), and modified Glasgow Prognostic Score." (PMID 39682288, 2024). "Each patient with ICI‐induced TIN had a malignant tumor, and this positively correlated with age and CRP levels." (PMID 38634742, 2024). "This supports our finding of CRP and albumin as early prognostic parameters at the time of cancer diagnosis." (PMID 38539528, 2024). "In this study, cancer patients with a good CRP response during antibiotic therapy presented lower mortality and a higher proportion of satisfactory therapeutic responses." (PMID 39272020, 2024). "SIRI and SII, which are usually assessed based on peripheral blood-based parameters (e.g., lymphocytes, CRP, monocytes, neutrophils, or PLT count), have been shown to be associated with several types of cancer." (PMID 39070943, 2024). "Given that CEA levels can rise in chronic inflammation, and that CRP is an acute-phase protein, it can be concluded that GSDM D is closely associated with the inflammatory response during the progression of cancer." (PMID 39766111, 2024). "FAs have also been shown to reduce acute phase proteins such as C-reactive protein in different types of cancer." (PMID 38674936, 2024). "CRP is an acute-phase protein produced by the liver in response to inflammation and is often elevated in cancer patients with systemic inflammation." (PMID 39335659, 2024). "Chronic inflammation and malignancies are intimately connected, and CRP is one of the most researched inflammatory indicators." (PMID 38384810, 2024). "A serum CRP value of 5 mg/dL was considered instrumental for identifying patients who should be provided multimodal care for cancer cachexia." (PMID 39765960, 2024). "A subgroup analysis excluding cancer patients was conducted to address the potential confounding factors related to cancer, as cancer is known to cause elevated NLR, D-Dimer, CRP, and PCT." (PMID 38792539, 2024). "The discussed study also analyzed the systemic inflammation of the body in patients with locoregional cancer, and statistically significantly higher levels of leukocytes and CRP were confirmed compared to the control group." (PMID 39458051, 2024). "CRP is widely recognized in oncology as a reliable biomarker for assessing survival, cancer risks, and tumor recurrence." (PMID 37765593, 2023). "In terms of the prognostic relevance of CRP, high serum CRP levels before surgery correlate with poor prognosis in various types of cancer." (PMID 39516365, 2023).
cancer (continued). "The prognostic role of CRP levels in CRC patients remains a matter of debate in studies of cancer-free general populations." (PMID 36996866, 2023). "Further research is necessary to explore these potential relationships and interactions, offering a more comprehensive understanding of the role of CRP in cancer treatment." (PMID 38104105, 2023). "TIA patients with active cancer presented with higher plasma levels of D-dimer, CRP, high-sensitive Troponin T, and INR at admission." (PMID 37840935, 2023). "Serum C-reactive protein (CRP) and albumin levels are representative of chronic inflammation and nutritional status in cancer patients." (PMID 37333829, 2023). "PTX3 is expressed and released by different cell types at the site of inflammation, e.g., innate immune cells, stromal cells, as well as cancer cells, in contrast with CRP or SAP, which are primarily produced within the liver due to IL-6 mediated inflammation." (PMID 38136377, 2023). "The eligibility of patients undergoing cancer immunotherapy for CRP apheresis has to be investigated." (PMID 37626775, 2023). "Previous studies revealed that the relevant biomarkers, such as the systemic inflammation score (SIS) and inflammatory marker C-reactive protein (CRP), can predict the prognosis of cancer patients." (PMID 37063918, 2023). "CRP changes the expression of proto-oncogenes and suppressor genes and immune regulation through different pathways, affecting cancer cell proliferation, migration, invasion, chemotherapy resistance and immune system resistance." (PMID 36923698, 2023). "The relationship between chronic inflammation, as measured by inflammatory circulating biomarkers including C‐reactive protein (CRP) and interleukin‐6 (IL‐6), and cancer incidence has recently been described in a systematic review and meta‐analysis." (PMID 36440611, 2023). "Other key mediators in the cancer-inflammatory relationship are C reactive protein (CRP) and albumin." (PMID 37460806, 2023). "For the patients diagnosed with cancer during the remaining follow‐up period, 34% had elevated CRP, 62% had elevated IL‐6 and 37% had elevated YKL‐40." (PMID 36440611, 2023). "Our objectives were to identify clinical correlates of longitudinal changes in CRP in the general population and to examine the relationship between changes in CRP levels over time with incident CVD, incident cancer, and all-cause mortality." (PMID 37019514, 2023). "While most research on the different isoforms of CRP has been carried out in cardiovascular and neurodegenerative disorders, as well as some autoimmune diseases, little is known about their role in cancer." (PMID 37006231, 2023). "These proteins belong to the family of fast-reacting proteins, such as C-reactive protein, whose usefulness in cancer has been widely proven." (PMID 38136377, 2023). "Since systemic inflammation is a hallmark of cancer cachexia, and because LCN-2 release is associated with inflammation, we determined the degree of systemic inflammation as expressed by the CRP to albumin ratio in the study groups." (PMID 37006254, 2023). "Plasma concentrations of the inflammatory biomarkers CRP, IL‐6 and YKL‐40 are associated with poor prognosis in patients with advanced cancer." (PMID 36440611, 2023). "By targeting inflammation and related prognostic biomarkers of cancer, including CRP and TNF-α, exercise holds promise for reducing and preventing CRF." (PMID 37507961, 2023). "CAR and the modified Glasgow and prognostic score, which comprises CRP and albumin concentrations, have been shown to have prognostic value for several cancers." (PMID 36875089, 2023). "We have previously shown with two independent cohorts that CRP levels >10 mg/L are linked to poor PFS and OS in ICI treated cancer patients and the likelihood of treatment benefit in these patients is very low (mPFS 2.0 months)." (PMID 37329173, 2023).
cancer (continued). "The aim of this study was to determine the accuracy and optimal cut-off value of CRP for anastomotic leakage in patients following esophagectomy for cancer." (PMID 37103558, 2023). "Positive correlations between YKL-40 and other biomarkers involved in cancer-promotion or systemic inflammation (IL-6, IL-8, and CRP) were identified in this study." (PMID 37744345, 2023). "Future studies should further evaluate the role of CRP in populations with cancer treated with ICIs as a potential guide for initial IMDC treatment." (PMID 37476185, 2023). "SAA1 and CRP are biomarkers of acute inflammation and cancer development; also, in earlier proteome analyses of BS patients, a decrease in the concentrations of both proteins was reported." (PMID 36979008, 2023). "Taken together, dNLR and CRP from baseline have prognostic and potentially predictive utility in the setting of cancer." (PMID 36673123, 2023). "Blood-based biomarkers measuring systemic inflammatory response such as the neutrophil-to-lymphocyte ratio (NLR) and C-reactive protein (CRP) were also evaluated as predictors of cancer outcomes in NMIBC." (PMID 37835862, 2023). "Chronic inflammation is closely related to cancer progression; thus, attention has focused on the relationship between elevated CRP and prognosis in cancer patients including PC." (PMID 37333829, 2023). "Among patients diagnosed with cancer within 3 months, 44% had elevated CRP, 60% had elevated IL‐6 and 45% had elevated YKL‐40." (PMID 36440611, 2023). "On the other hand, the number and ratio of immune cells by blood tests or blood levels of inflammatory substances such as C-reactive protein (CRP) are known as prognostic factors in cancer." (PMID 38143707, 2023). "We also set out to evaluate the prognostic value for other markers of cancer progress such as fatigue, change in albumin levels and CRP/albumin ratio." (PMID 37880704, 2023). "Cox regression model for heart disease and cancer mortality among the 4 groups at CRP 0.3 and 1.0 mg/dL." (PMID 38293298, 2023). "A number of inflammatory indicators are reportedly prognostic factors of cancers, including the C-reactive protein-to-albumin ratio, neutrophil-to-lymphocytes ratio, and others." (PMID 37592262, 2023). "In previous studies by our colleagues, high SCC-Ag and C-reactive protein levels can predict advanced cancer stages and adverse survival outcomes in patients with OSCC and recurrent diseases." (PMID 37173956, 2023). "Several investigators have reported associations between an elevated CRP level and poor survival in ICI-treated cancer patients." (PMID 38049762, 2023). "In the present study, as in previous reports, Alb, CRP, and blood glucose levels at three months separated the survival curves into groups with significantly different survival rates in cancer patients." (PMID 37242217, 2023). "GPS, which can predict the postoperative outcomes of various cancers, is a combination of serum C-reactive protein (CRP) and albumin levels, which are biomarkers of systemic inflammatory response and nutritional status, respectively." (PMID 37146004, 2023). "Patients with active cancer showed multiterritorial infarcts more frequently, and usually presented with higher D-dimer, CRP, LDH, and INR and lower albumin, Hb, LDL cholesterol, total cholesterol and thrombocytes." (PMID 37021282, 2023). "This study revealed that increased t-HHLA2 expression is related to lower NLR, and increased s-FAP expression is related to higher CRP levels, which is also a cancer biomarker." (PMID 36598731, 2023). "Several prognostic scores have been developed to aid in the assessment of cancer prognosis, some of which are based on serum CRP and albumin levels, such as the Glasgow prognostic score." (PMID 37173358, 2023). "High levels of C-reactive protein (CRP), interleukin 6 (IL- 6), and interleukin 10 (IL-10) are associated with poor performance, weight loss, and worse prognosis in cancer patients." (PMID 38067294, 2023).